PRMT5 (protein arginine methyltransferase 5)
Diseases named in the same sentence as PRMT5 in open-access papers (continued):
Sharing a sentence is not in itself a finding about the gene and the disease.
breast carcinoma (continued). "To summary, PRMT5 is related to poor clinical outcome and the transition of CSC in breast cancer, which provide a potential target for inhibition of breast cancer metastasis." (PMID 33193750, 2020). "PRMT5 is heterogeneously expressed in TNBC and high PRMT5 expression correlates with poor prognosis within this breast cancer subtype." (PMID 30957988, 2019). "In summary, our findings demonstrated that PRMT5-mediated histone modifications could possibly regulate EMT and invasion of breast cancer cells under hypoxia." (PMID 41150697, 2025). "Firstly, to understand TCF3 splicing pattern and its dependency on PRMT5 in breast cancer hypoxia, we performed qRT-PCR analysis with or without GSK591 treatment using primers designed specifically against exons 18A and 18B." (PMID 41150697, 2025). "PRMT5 regulates BRCA1 mRNA stability by promoting nuclear translocation of ALKBH5, which demethylates BRCA1 transcripts under doxorubicin treatment, thereby enhancing repair capacity and reducing chemotherapy efficacy in breast cancer cells." (PMID 41204384, 2025). "Additionally, the data in GSE65194 showed that PRMT1, PRMT3, CARM1, PRMT5, and PRMT6 were highly expressed in basal-like breast cancer." (PMID 38476024, 2024). "Two PRMT5 inhibitors (GSK3326595 and JNJ-64619178) inhibit the growth of melanoma tumours in murine model and are currently being investigated as the treatment of solid tumours, Non-Hodgkin’s lymphoma and breast cancer." (PMID 37731322, 2023). "PRMT5 expression was moderately to strongly correlated (Pearson score ≥ 0.4) with established DDR genes such as BRCA1, BRCA2, RAD51, RAD51D, RAD51AP1, FANCA, and FANCI across 125 ovarian and breast cancer cell lines." (PMID 37861290, 2023). "Importantly, our investigational clinical PRMT5 inhibitor PRT543 displayed significant in vivo efficacy when combined with olaparib in multiple preclinical CDX and PDX ovarian and breast cancer models." (PMID 37861290, 2023). "Thus, our data highlight for the first time the potential utility of clinically relevant PRMT5 inhibitors for the treatment of PARP inhibitor–resistant ovarian and breast cancers." (PMID 37861290, 2023). "Thus, we sought to evaluate therapeutic opportunities for our PRMT5 inhibitors (C220 and PRT543) in ovarian and breast cancers, where PARP inhibitors are clinically approved in patients with HRD tumors." (PMID 37861290, 2023). "The role of PRMT5 and LSD1 in breast cancer progression was evaluated both in vivo and in vitro." (PMID 35655230, 2022). "Like MEP50, we found that PRMT5 mRNA is associated with RFS only in TNBC and luminal B patients and not in the other breast cancer subgroups." (PMID 36230689, 2022). "We observed a positive correlation between MEP50 and PRMT5 mRNA levels in our cohort in the whole breast cancer population but not within the different breast cancer subgroups, although a tendency was observed for the luminal B subgroup (p = 0.053)." (PMID 36230689, 2022). "To investigate whether the combined inhibition of PRMT5 and LSD1 would synergistically impede breast cancer progression, we employed a PRMT5 inhibitory compound EPZ015666 and a selective LSD1 inhibitor SP2509." (PMID 35655230, 2022). "We further analyzed the PRMT5 and LSD1 co-expression in distinct breast cancer subtypes." (PMID 35655230, 2022). "Importantly, combined inhibition of PRMT5 and LSD1 synergistically impedes the EMT and breast cancer progression." (PMID 35655230, 2022). "In lung cancer and breast carcinoma cells, WDR5 could recruit protein arginine methyltransferase 5 (PRMT5) complexes to target gene promoters, enhancing the deposition of H3K4me3 to promote gene transcription and cancer cell invasion." (PMID 35371306, 2022).
breast carcinoma (continued). "Similar with PRMT5, PRMT7 could promote the EMT process and increase cell migration in breast cancer cells." (PMID 33193750, 2020). "Arginine methylation of EGFR by PRMT5 occurs on a residue proximal to the auto-phosphorylated tyrosine following EGF-stimulation and thereby facilitates SHP recruitment and reduces ERK-activation and proliferation/migration of breast cancer cells." (PMID 32743345, 2020). "From a database analysis, PRMT5, MEP50, and GLI1 target genes are all upregulated in known HH signaling pathway-activated cancers, including SCLC, gastric cancer, skin basal carcinoma, and breast cancer." (PMID 32859041, 2020). "In addition, because breast cancer stem cells (BCSCs) are enriched in TNBC8 and play a role in resistance to chemotherapies, we investigated the effect of PRMT5 inhibition on an indicator of breast cancer cell stemness." (PMID 30957988, 2019). "Indeed, PRMT5 is expressed at lower levels in the nucleus of TNBC than in those of healthy breast tissues, HER2+, and luminal breast cancers." (PMID 30957988, 2019). "In an orthotopic breast cancer model, co-expression of PDCD4 and PRMT5 accelerates tumor growth." (PMID 27556302, 2016). "Interestingly, these authors did not detect significant changes of SDMA on AKT2/3 in breast cancer upon PRMT5 inhibition, which is consistent with our observation." (PMID 35803962, 2022). "Finally, examination of human cancer samples showed that expression of PRMT5 and MEP50, as well as GLI1 target genes was upregulated in small cell lung carcinoma, gastric cancer, other known HH signal-activated cancers including skin basal cell carcinoma 3 and breast cancer." (PMID 30675521, 2019). "Collectively, our data provide compelling evidence in vitro and in vivo that PRMT5 inhibitors could be used in combination clinically approved PARP inhibitors and chemotherapies for the treatment of ovarian or breast cancer, potentially irrespective of genomic HRD status." (PMID 37861290, 2023).
lung carcinoma (83 papers, 2013 to 2026). "Posttranslational arginine methylation of M×i1by PRMT5 facilitates the ubiquitination and degradation of M×i1by binding of the β-Trcp ligase, causing radio resistance in lung cancer." (PMID 40701777, 2025). "High levels of PRMT5 expression in lung cancer have been associated with poor prognosis, and inhibition of PRMT5 can affect the growth cycle of lung cancer cells by inhibiting the phosphorylation of AKT1." (PMID 37400960, 2023). "Through histone methylation of the miR‐99 family and activation of Erk1/2 and Akt pathway, PRMT5 has been implicated in the progression of lung cancers." (PMID 35747993, 2023). "Prmt5 has been reported to be associated with the development of multiple cancers, such as lung cancer, cervical cancer, glioblastoma and liver cancer, where it boosts cancer cell hyperproliferation." (PMID 37533053, 2023). "Our findings identified the oncogenic role of PRMT5 in human lung cancer and elucidated a novel mechanism underlying the modulation of the Smad7‐gp130‐STAT3 axis by PRMT5 in those cancer types with aberrantly hyperactivation of STAT3." (PMID 34026434, 2021). "Elevated expression levels of PRMT5 and its enhanced methyltransferase activity have also been implicated in the proliferation of lung cancer cells." (PMID 34200178, 2021). "Nevertheless, the exact role of PRMT5 in human lung cancer cell proliferation and the underlying molecular mechanism remains largely obscure." (PMID 30461193, 2019). "However, the precise role of PRMT5 in regulating angiogenesis to promote lung cancer cell metastasis and the underlying molecular mechanisms are not fully understood." (PMID 37400960, 2023). "MTA in turn inhibits PRMT5, supporting the hypothesis that MTAP deficient lung cancer may respond better to PRMT5 inhibition." (PMID 35747993, 2023). "The survival analyses of publicly available lung cancer data revealed that an increased level of PRMT5 gene expression was significantly linked to worse overall survival (OS) in lung adenocarcinoma with the pooled hazard ratio (HR) of 1.31 (95% confidence interval [CI] 1.03–1.68, p-value of 0.028)." (PMID 34200178, 2021). "However, the exact role of PRMT5 in human lung cancer cell proliferation and the underlying molecular mechanism remain largely elusive." (PMID 34026434, 2021). "To determine the association between PRMT5 gene expression level and survival of lung cancer patients, and to identify the major functional pathways related to PRMT5 activity in lung adenocarcinoma, we carried out bioinformatic analyses using the publicly available data." (PMID 34200178, 2021). "We hypothesized that PRMT5 inhibition may cause immune-resistance in addition to direct antitumor effects in lung cancer." (PMID 35111150, 2021). "To investigate whether PRMT5 is implicated in lung cancer cell proliferation, we delivered the PRMT5 and scramble shRNA into A549 and H1299 cells by lentivirus and generated PRMT5 stable knockdown cells." (PMID 30461193, 2019). "Interestingly, exogenous KLF5 only partially rescued lung cancer cell proliferation in PRMT5‐deficient cells, which may be due to additional roles of KLF5, such as transcriptional regulation of specific targets." (PMID 37461162, 2023). "In addition, the high expression of PRMT5 in lung cancer is associated with poor prognosis." (PMID 35531958, 2022). "This study provides the first comprehensive analysis of the PPM1B/MP/PRMT5/histone signaling pathway in human lung cancer tissues, revealing a novel oncogenic mechanism that distinguishes between ADC and SCC subtypes." (PMID 41301499, 2025). "We included two breast and one lung cancer dataset for comparison as these tumour types are the focus of PRMT5 inhibitor phase I/II trials for adult cancers." (PMID 40823091, 2025).
lung carcinoma (continued). "In lung cancer, PRMT5 suppressed the transcription of miR‐99 by SDMA of histone H4R3, leading to increased expression of epidermal growth factor receptor 3 and activation of Erk1/2 and Akt, thus facilitating the metastasis." (PMID 40384988, 2025). "The development of clinically relevant inhibitors for specific PRMTs, particularly for PRMT5, has thus progressed at a phenomenal rate with several Phase I/II clinical trials initiated for adult haematological, breast and lung cancer." (PMID 40823091, 2025). "Our findings confirm that PRMT5 plays a central oncogenic role in lung cancer through both increased expression and enhanced activating phosphorylation at Thr80." (PMID 41301499, 2025). "This suggests that the most modern lung cancer therapy—the immune checkpoint inhibition of PD-L1—can be enhanced with PRMT5 inhibitors, supporting the development of PRMT5-targeted therapies and the application of combined therapies." (PMID 41301499, 2025). "In lung cancer, PRMT5 downregulates miR-99 family, elevating FGFR3 and activating ERK/AKT signaling to promote tumor growth." (PMID 41204384, 2025). "PRMT5 is a frequently studied therapeutic target, and the effectiveness of PRMT5 inhibitors in lung cancer cell lines or xenografts has shown promising results." (PMID 41301499, 2025). "In conclusion, our study reveals that the PPM1B/MP/PRMT5/histone oncogenic signaling pathway plays a role in lung cancer development and progression." (PMID 41301499, 2025). "In lung cancer cells, PRMT5 inhibition with AMI-1 synergizes with cisplatin to reduce cell viability and induce apoptosis." (PMID 41204384, 2025). "To investigate the efficacy of PRMT5 inhibition, we treated oral and lung cancer cells with single and combined PRMT5 and PRMT1 inhibitors (PRMT5/1i)." (PMID 38709899, 2024). "In lung cancer cells, downregulation of PRMT5 or overexpression of PRMT1 promotes apoptosis induced by docetaxel and pemetrexed by modulating the degradation of the anti-apoptotic protein CFLARL." (PMID 38525426, 2024). "PRMT5, identified as an oncogene, demonstrates elevated levels across various cancer types, including lung cancer, melanoma, glioma, prostate cancer, and lymphoma." (PMID 38791992, 2024). "In lung cancer, high levels of cytoplasmic PRMT5 are correlated with a higher grade and poorer prognosis in aggressive non-small-cell lung carcinomas, whereas nuclear PRMT5 is more frequently detected in non-aggressive carcinoid tumors." (PMID 38791992, 2024). "Other HMTs, such as SET domain containing 8 (SETD8), SET and MYND domain containing 3 (SMYD3), SETDB1, and PRMT5, are also overexpressed in lung cancer, correlating with the tumor’s aggressiveness and clinical characteristics." (PMID 38525426, 2024). "Previous studies discussed PRMT5′s role in modulating the activity of ERK in glioblastoma neurospheres and lung cancer, with ERK being encoded by the MAPK3 gene." (PMID 38666828, 2024). "To define the biological functions of PRMT5 in lung cancer, we first evaluated the relative expression levels of PRMT5 in lung tumor tissues and normal tissues." (PMID 37400960, 2023). "To explore the expression and potential function of KLF5 and PRMT5 in lung cancer, we first evaluated the mRNA expression of KLF5 in lung cancer tissues and matched normal tissues." (PMID 37461162, 2023). "PRMT5 has also been shown to promote metastasis of lung cancer cells by activating the AKT1 and ERK signaling pathways." (PMID 37400960, 2023). "Mechanistically, the dimethylation of KLF5 by PRMT5 promotes the maintenance and proliferation of lung cancer cells at least partially by stabilising KLF5 via regulation of the Akt/GSK3β signalling axis." (PMID 37461162, 2023). "Taken together, our molecular analysis revealed a novel mechanism underlying the regulation of KLF5 protein expression and function in lung cancer, which involves arginine methylation by PRMT5 and proteasome‐mediated degradation." (PMID 37461162, 2023).
lung carcinoma (continued). "Our study provides compelling evidence of the close association between PRMT5 and angiogenesis/EMT and highlights the potential of targeting PRMT5 activity as a promising therapeutic approach for treating lung cancer with abnormal angiogenesis." (PMID 37400960, 2023). "We found that PRMT5 positively correlated with HIF-1α and PI3K/Akt signaling pathway in lung cancer, suggesting a potential association between these genes and pathways." (PMID 37400960, 2023). "PRMT5 mRNA expression was much higher in lung tumor tissues than in normal tissues, indicating that PRMT5 is up-regulated in lung cancer." (PMID 37400960, 2023). "Previous studies have shown that PRMT5 was overexpressed in lung cancer and played a key role in governing the EMT and metastasis." (PMID 37461162, 2023). "Experiments with human lung cancer cells lines have revealed that PRMT5 inhibitor molecules promoted lung cancer cell apoptosis and increased chemosensitivity." (PMID 35747993, 2023). "Recent studies have shown that PRMT5 is a potential therapeutic target in different types of human cancers, including lung cancer." (PMID 37461162, 2023). "The reasons for choosing these cells were (a) reports of frequent radioresistance in glioblastoma and lung cancer patients, and (b) PRMT5-mediated promotion of DNA damage repair in both A549 and U87MG cells." (PMID 36959798, 2023). "More and more evidence indicates that PRMT5 is a carcinogenic protein that plays a pivotal role in various human cancers, especially in lung cancer." (PMID 37461162, 2023). "All these observations strongly indicate that controlling PRMT5 protein expression level or its enzyme activity is a promising therapeutic method to prevent human cancers, particularly lung cancer." (PMID 37461162, 2023). "Here, we show that PRMT5 is overexpressed in lung cancer cells and tissues, and its expression is triggered by hypoxia." (PMID 37400960, 2023). "Our study showed that PRMT5 was highly expressed in human lung cancer tissues and correlated with the progression of lung tumors and patient survival rates." (PMID 37400960, 2023). "Altogether, our findings suggest that PRMT5 regulates lung cancer cell EMT and metastasis, at least in part, via promoting angiogenesis by controlling HIF-1α/VEGFR/Akt/eNOS signaling pathway." (PMID 37400960, 2023). "Our results also demonstrated that PRMT5 was a critical epigenetic regulator for KLF5 to promote lung cancer cell growth." (PMID 37461162, 2023). "Last, LUBAC proteins play a regulatory role in the enzymatic activity of PRMT5 and histone methylation through interactions in melanoma and lung cancer, respectively." (PMID 38017534, 2023). "PRMT5 was shown to be highly elevated in human lung cancer cells and tissues, and inhibiting its expression decreased the proliferation of tissue-cultured lung adenocarcinoma A549 cells significantly." (PMID 36364261, 2022). "PRMT5 is a promising predictive biomarker for lung cancer patients with high expression in lung tissues, according to numerous pieces of research published in recent years." (PMID 36364261, 2022). "Repression of MTAP‐dependent symmetric dimethylation mediated by PRMT5 increases vimentin protein stability and leads to invasion and metastasis in MTAP‐deficient lung cancer." (PMID 35766227, 2022). "A growing body of evidence suggests that targeting PRMT5 has therapeutic value in the treatment of human lung cancer." (PMID 36364261, 2022). "Additional studies have reported that type I PRMT inhibitors synergize with inhibitors targeting PARP in TNBC and lung cancer; PRMT5 in leukemia, pancreatic, and lung cancer; FLT3 kinase in leukemia; or anti-PD-1/PD-L1 in various cancer types." (PMID 35053470, 2022). "We verified PRMT5 expression in lung cancer and found that it was increased in lung cancer cell lines compared with the embryonic fibroblast cell line, MRC-5." (PMID 35111150, 2021).